S100A16 (S100 calcium binding protein A16)
Diseases named in the same sentence as S100A16 in open-access papers (continued):
Sharing a sentence is not in itself a finding about the gene and the disease.
breast carcinoma (continued). "At the sub-cellular level, the S100A16 protein was found to be localised predominantly in the cell membrane in breast cancer cells." (PMID 37509106, 2023). "Functionally, overexpression of S100A16 was found to promote proliferation, colony formation, migration, and invasion capabilities of breast cancer cells as compared to control cells." (PMID 37509106, 2023). "S100A16 expressions, mutually with S100A14, have been linked to a dangerous condition in patients with breast cancer; both proteins, in cooperation, can increase the aggressive activity of breast cancer cells via cytoskeleton functions." (PMID 36613714, 2022). "S100A16/S100F is a 10–12 kDa protein with the EF-hand Ca2+ binding motif significantly regulated in lung, ovarian, prostate, and breast cancers." (PMID 36613714, 2022). "While in this study the expression of this protein was significantly down-regulated, previous study have shown that the upregulation of S100A16 expression promotes epithelial mesenchymal transition via the Notch1 pathway in breast cancer." (PMID 31877708, 2019). "Similarity,higher expression of S100A16 predicted worse OS in breast cancer by promoting epithelial-mesenchymal transition." (PMID 30558666, 2018). "The second aim was to explore the molecular mechanisms by which S100A14 and S100A16 contribute to the progression of breast cancer." (PMID 25884418, 2015). "We investigated the interactions of S100A14, S100A16 with other binding protein(s) in breast cancer cells and examined the function of these molecules in cellular proliferation, migration and invasion." (PMID 25884418, 2015). "To further analyze the role of S100A14 and S100A16 proteins in breast cancer, we next examined the mRNA expression levels of S100A14 and S100A16 in human breast cancer cell lines by using qRT-PCR." (PMID 25884418, 2015). "The first aim of the present study was to investigate the clinical significance of S100A14 and S100A16 expression in the prognosis of breast cancer patients." (PMID 25884418, 2015). "In a clinical study, an immunohistochemical analysis of S100A14 and S100A16 expression in archival specimens of primary tumors of 167 breast cancer patients was performed." (PMID 25884418, 2015). "Since cellular localization of S100 proteins is important for their function, we performed a detailed analysis of the subcellular localization of S100A14 and S100A16 proteins in breast cancer cells." (PMID 25884418, 2015). "All of these findings indicate that S100A14 and S100A16 expression augments the malignant phenotype of breast cancer." (PMID 25884418, 2015). "To investigate the function of S100A16 in breast cancer, we first documented here that S100A16 was over-expressed in breast cancer tumors." (PMID 25287362, 2014). "Further examination demonstrated that up-regulation of S100A16 promoted EMT via Notch1 pathway in breast cancer cell line MCF-7." (PMID 25287362, 2014). "The mean expression level of S100A16 mRNA in breast cancer tissue was also significantly higher than that in adjacent non-cancerous tissue using a scatter plot." (PMID 25287362, 2014). "In the present study, we first documented here that overexpression of S100A16 occurred in the human breast cancer tumors compared with the paired adjacent normal tissue." (PMID 25287362, 2014). "It has been reported that S100A16 is up-regulated in various malignant tumors, however, the role of S100A16 gene in human breast cancer is yet to be elucidated." (PMID 25287362, 2014). "It is also under study to follow up the patients with S100A16 overexpresstion to confirm the function of S100A16 in the progression of breast cancer." (PMID 25287362, 2014). "Moreover, detailed immunohistochemical analysis of S100A16 in breast cancer patients revealed S100A16 as a compelling biomarker which predicted poorer prognosis and was correlated with both tumor size and increased incidence of lymph node metastasis." (PMID 40846689, 2025).
breast carcinoma (continued). "Indeed, modulation of S100A16 expression profoundly impacted the regulation of rRNA transcription as well as modulated EMT in metastatic breast cancer cells." (PMID 40846689, 2025). "In breast cancer, the overexpression of S100A16 promotes cell proliferation, colony formation, tumor cell invasion, and migration through the epithelial–mesenchymal transition (EMT) pathway and transcription factors such as Notch1 and zinc finger E-box-binding homeobox 1/2." (PMID 37833982, 2023). "Furthermore, S100A16 coexpression with S100A14 is associated with poor prognosis of breast cancer patients and invasive activity of breast cancer cells, promoted by an interaction with the cytoskeleton dynamics." (PMID 34639239, 2021). "Besides breast cancer, S100A16 was identified as an important prognostic marker for colorectal cancer and was shown to be significantly overexpressed in both prostate cancer tissues and cells lines, compared to normal controls." (PMID 31877708, 2019). "One previous study found that S100A16 could promote EMT in breast cancer cells by elevating the expression of transcription factors Notch1, ZEB1, and ZEB2." (PMID 29746588, 2018). "In breast cancer, S100A16 upregulation could promote epithelial-mesenchymal transition (EMT) via the Notch1 pathway, thereby enhancing cancer cell invasion." (PMID 29746588, 2018). "Our findings suggest that S100A14 and S100A16 protein expression may be predictive biomarkers for poorer prognosis of breast cancer patients." (PMID 25884418, 2015). "In addition, our findings indicate that S100A14 and S100A16 can promote invasive activity of breast cancer cells via an interaction with cytoskeletal dynamics." (PMID 25884418, 2015). "However, our multivariate analysis showed that expression of S100A14, and co-expression of S100A14 and S100A16, are independent prognostic factors for breast cancer." (PMID 25884418, 2015). "S100A14 and S100A16 might be prognostic biomarkers and potential therapeutic targets for breast cancer." (PMID 25884418, 2015). "It is unclear the association among S100A16, ER, and HER2 in breast cancer." (PMID 25287362, 2014). "Till now, the function of S100A16 in the breast cancer remains to be elucidated." (PMID 25287362, 2014). "All these data indicated that the S100A16 gene might be closely associated with EMT and promote invasion and metastases during the progression of human breast cancer." (PMID 25287362, 2014). "Importantly, we describe a unique role of S100A16 in the nucleolus of breast cancer cells and disruption of protein content in the nucleolus, as evidenced by S100A16 modulation, underscores the importance of the nucleolus in potentiating metastasis in breast cancer." (PMID 40846689, 2025). "Additionally, we provide compelling evidence that the nucleolar proteome has a distinct and unique role in promoting metastasis, as the most differentially expressed protein in the nucleolus of metastatic breast cancer cells, S100A16, is a potent promoter of metastasis." (PMID 40846689, 2025). "Because S100A14 and S100A16 can promote cancer cell motility and invasion via modulation of cytoskeletal dynamics, these proteins could be novel target molecules for therapeutic strategies in breast cancer patients." (PMID 25884418, 2015). "Thus, interaction between S100A14 and S100A16 proteins may be the reason for the strong correlation of their expression in human breast cancer tissues." (PMID 25884418, 2015). "Thus, S100A14 and S100A16 proteins may promote the malignant nature of breast cancer by acting in cooperation with each other or with other binding proteins on the cell membrane." (PMID 25884418, 2015). "Interestingly, over-expression of S100A16 was observed particularly in the invasive front in breast cancer tissues, which indicated that S100A16 might be related to EMT." (PMID 25287362, 2014). "All of these findings imply that S100A16 may be involved in the progression of breast cancer." (PMID 25287362, 2014).
breast carcinoma (continued). "Our results suggested that S100A16 may be involved in the progress of breast cancer." (PMID 25287362, 2014). "All together, our data indicated that S100A16 had a potential function to regulate some embryonic transcription factors to promote EMT in breast cancer cells which may be an important target site for the therapy of breast cancer." (PMID 25287362, 2014). "Our previous set of results revealed that S100A16 impinges upon EMT and drives the invasive potential of breast cancer cells." (PMID 40846689, 2025). "Aligned with these reports, our current data emphasizes the ability of S100A16 to modulate EMT and promote the metastatic potential of breast cancer." (PMID 40846689, 2025). "In an experimental study, the subcellular localization and function of these molecules was examined by using the human breast cancer cell lines MCF7 and SK-BR-3, both of which highly express S100A14 and S100A16 proteins." (PMID 25884418, 2015). "Immunohistochemical analysis of 167 breast cancer cases showed strong cell membrane staining of S100A14 (53% of cases) and S100A16 (31% of cases) with a significant number of cases with co-expression (p < 0.001)." (PMID 25884418, 2015). "More investigation is required to find the relationship of S100A16 with two important clinical biomarkers ER and HER2 in breast cancer." (PMID 25287362, 2014). "In summary, the current study demonstrated that overexpression of S100A16 gene promoted EMT via Notch1/ZEB1, ZEB2/EMT pathway in breast cancer cells." (PMID 25287362, 2014). "As such, our study provides compelling evidence underscoring the key role the nucleolus plays in metastasis; more specifically, nucleolar S100A16 promotes metastasis by enhancing ribosome biogenesis-driven EMT, representing a potential therapeutic target in metastatic breast cancer." (PMID 40846689, 2025). "Interestingly, co-expression of S100A16 and S100A14, another member of the S100 protein family, was an independent prognostic factor for poor patient outcome in breast cancer." (PMID 37509106, 2023). "This indicates that γT3 has a potential effect on S100A16, which might negatively regulate some embryonic transcription factors that promotes EMT in breast cancer cells, which are known to be an important target site for the therapy of breast cancer." (PMID 31877708, 2019). "This analysis revealed that S100A14 and S100A16 proteins were expressed mainly on the membrane of breast cancer cells, while no or faint staining was seen in normal epithelial cells of each sample (representative staining)." (PMID 25884418, 2015). "To determine the contribution of S100 protein expression to breast cancer, we first used immunohistochemistry to analyze S100A14 and S100A16 protein expression in tissue samples of 167 patients who underwent surgical resection for primary invasive breast cancer." (PMID 25884418, 2015). "In this study, we observed that S100A16 was expressed in higher levels in human breast cancer tissues compared with paired adjacent non-cancerous tissues." (PMID 25287362, 2014). "We measured S100A16 expression in 20 breast cancer tissue samples compared with paired adjacent non-cancerous tissue using qRT-PCR." (PMID 25287362, 2014). "Among the tested cell lines, it was interesting to find that S100A16 protein was mainly expressed in epithelial breast cancer cell lines but not in mesenchymal breast cancer cell lines." (PMID 25287362, 2014). "Interestingly, a study had shown that co-expression of S100A16 and S100A14 in breast cancer promoted the invasive ability of cancer cells; overexpression and knockdown of S100A14 could affect the expression of S100A1649." (PMID 38762700, 2024). "Besides, Immunostainings for S100A16 were performed in breast cancer tissues and the matched non-cancerous tissues." (PMID 25287362, 2014).
breast carcinoma (continued). "In addition, to our knowledge, clinicopathological studies of the expression of S100A16 (except for reports of global expression profiles), or of the co-expression of S100A14 and S100A16 in breast cancer patients have not been reported." (PMID 25884418, 2015).
gastric cancer (13 papers, 2008 to 2025). A primary or metastatic malignant neoplasm involving the stomach. "MiR-6884-5p was reported to directly target S100A16 in gastric cancer cells, thus miR-6884-5p was also expected to directly target S100A16 in NSCLC." (PMID 38271114, 2024). "In line with our findings, downregulation of S100A16 inhibits the proliferation and migration of tumor cells in pancreatic and gastric cancers." (PMID 36224471, 2022). "We observed that S100A16 expression is dramatically increased in gastric cancer tissues compared with adjacent normal tissues, and S100A16 elevation is a significant prerequisite for GC proliferation, invasion, and migration." (PMID 34650982, 2021). "A study on gastric cancer found that overexpression of S100A16 promotes the proliferation and migration of gastric cancer cells both in vitro and in vivo, indicating that S100A16 is a promising candidate biomarker for early diagnosis and prediction of metastasis in gastric cancer." (PMID 40481236, 2025). "MiR-6884-5p was reported to directly target S100A16 to regulate gastric cancer cells." (PMID 38271114, 2024). "In gastric cancer, decreased S100A16 expression is involved in miR-6884-5p and ADAMTS19 (A Disintegrin and Metalloproteinase with Thrombospondin motifs 19) inhibition of GC cells migration, invasion, and EMT, however, the role of S100A16 itself in GC metastasis has not been fully clarified yet." (PMID 34650982, 2021). "Moreover, miR-6884-5p directly targeted S100A16 to regulate gastric cancer, which gave us a hint that miR-6884-5p might also target S100A16 to modulate NSCLC, based on the key role of S100A16 in lung-related cancer." (PMID 38271114, 2024). "Using publicly available transcriptome datasets such as GEPIA and UALCAN, You and co-authors reported a significantly increased expression of S100A16 mRNA in gastric cancer (GC) tissue as compared to normal gastric tissue." (PMID 37509106, 2023). "Proteomics analysis in gastric cancer identified ZO2, a junction protein known to regulate metastasis, to interact with S100A16." (PMID 40846689, 2025). "Together, ZO-2 inhibition participates in the effects of S100A16 on invasion, migration and EMT phenotype of gastric cancer cells." (PMID 34650982, 2021). "Importantly, S100A16 was shown to promote degradation of ZO2, leading to EMT and enhanced migration and invasion of gastric cancer cells." (PMID 40846689, 2025).
colorectal cancer (10 papers, 2018 to 2025). A primary or metastatic malignant neoplasm that affects the colon or rectum. "Three proteins identified by MR, S100A16, S100A14 and PDE5A, might share causal variables with HER-positive breast cancer and colorectal cancer." (PMID 38762700, 2024). "However, high membrane S100A16 predicted better OS in colorectal cancer as well as oral squamous cell carcinoma." (PMID 30558666, 2018). "Interestingly, the results of colocalization analysis showed that S100A16 (coloc, PP.H4.abf = 0.933), S100A14 (coloc, PP.H4.abf = 0.913), and PDE5A (coloc, PP.H4.abf = 0.855) had the shared causal variation with HER-positive breast and colorectal cancers, respectively." (PMID 38762700, 2024). "Except in oral squamous cell and colorectal cancer, where it is not overexpressed, S100A16 is upregulated in several tumor types, promoting increased cell proliferation, invasion, and metastasis through multiple molecular pathways, including PI3K-Akt, MAPK-ERK, JNK/p38, and EMT signaling." (PMID 40846689, 2025). "Ultimately, based on our analysis, S100A16 and S100A14 were validated as potential second-class drug targets for HER-positive breast cancer, PDE5A as potential first-class drug targets for colorectal cancer, and MIA as potential second-class drug targets for non-small cell lung cancer." (PMID 38762700, 2024).
lung adenocarcinoma (9 papers, 2018 to 2024). A carcinoma that arises from the lung and is characterized by the presence of malignant glandular epithelial cells. "It has been widely reported that higher S100A16 mRNA expression in lung adenocarcinoma was significantly associated with poorer survival, and the subcellular localization of S100A16 and S100A16 mRNA expression levels are prognostic markers in LUAD." (PMID 38028153, 2023). "In lung adenocarcinoma, S100A16 expression was associated with vessel invasion and poor outcome and confirmed as an independent prognostic marker." (PMID 30558666, 2018). "In lung adenocarcinoma, S100A16 was found to be a prognostic marker for platinum-based adjuvant chemotherapy in an immunohistochemical study." (PMID 37833982, 2023). "Then, we examined S100A16 expression and its DNA methylation in 53 lung adenocarcinoma cell lines, by using data from the CCLE." (PMID 29746588, 2018). "S100A16 was expressed in lung adenocarcinoma (AC) tissues with poor prognosis." (PMID 33224891, 2020). "Two recent studies (N = 170 and N = 65 respectively) observed that S100A16 is significantly upregulated in lung adenocarcinoma (LUAD) and might be an independent prognostic indicator of poor OS." (PMID 29746588, 2018). "In this study, we explored the independent prognostic value of S100A16 in terms of overall survival (OS) and recurrence-free survival (RFS) by performing a retrospective study, using data in The Cancer Genome Atlas (TCGA)-lung adenocarcinoma (LUAD)." (PMID 29746588, 2018).
bladder cancer (7 papers, 2019 to 2023). "A recent evidence showed that the expression of S100A16 was negatively correlated with the overall survival of bladder cancer patients." (PMID 31877708, 2019).